MMP14 (matrix metallopeptidase 14)
Description:
Endopeptidase that degrades various components of the extracellular matrix such as collagen. Essential for pericellular collagenolysis and modeling of skeletal and extraskeletal connective tissues during development (By similarity). Activates progelatinase A/MMP2, thereby acting as a positive regulator of cell growth and migration. Involved in the formation of the fibrovascular tissues in association with pro-MMP2. May be involved in actin cytoskeleton reorganization by cleaving PTK7. Acts as a regulator of Notch signaling by mediating cleavage and inhibition of DLL1. Cleaves ADGRB1 to release vasculostatin-40 which inhibits angiogenesis. Acts as a negative regulator of the GDF15-GFRAL aversive response by mediating cleavage and inactivation of GFRAL.
Synonyms: MMP-14; MT-MMP 1; MTMMP1; MT1-MMP; MT1MMP; MMP-X1; MT-MMP; WNCHRS
Tractability: Small molecule: a drug acting on it is in phase 2 or 3 trials; a structure with a bound ligand is known; a high-quality ligand is known; it belongs to a druggable protein family. Antibody: UniProt places it where antibodies can reach, with high confidence; its Gene Ontology location is reachable by antibodies, with high confidence; UniProt predicts a signal peptide or a membrane-spanning region. PROTAC: ubiquitination databases record sites on it; its protein half-life has been measured; a small molecule that binds it is known.
Target class: Metallo protease; Metallo protease M10A subfamily; Metallo protease MAM clan; Protease; Enzyme
Gene: Protein-coding gene on chromosome 14 (22,836,532 to 22,849,041, forward strand). Ensembl gene ENSG00000157227.
Subcellular location: Cell membrane; Melanosome; Cytoplasm
Subcellular location (Human Protein Atlas): Cytosol; Intermediate filaments
Pathways (Reactome):
Extracellular matrix organization: Activation of Matrix Metalloproteinases; Collagen degradation; Degradation of the extracellular matrix
Cellular responses to stimuli: High laminar flow shear stress activates signaling by PIEZO1 and PECAM1:CDH5:KDR in endothelial cells
Signal Transduction: TGFBR3 PTM regulation
Gene Ontology:
Molecular function: endopeptidase activity; metalloaminopeptidase activity; metalloendopeptidase activity; protein binding; serine-type endopeptidase activity; zinc ion binding; integrin binding; metallopeptidase activity
Biological process: endodermal cell differentiation; negative regulation of GDF15-GFRAL signaling pathway; positive regulation of cell growth; positive regulation of cell migration; protein catabolic process; proteolysis; regulation of protein localization to plasma membrane; zymogen activation; cell motility; collagen catabolic process; extracellular matrix disassembly; extracellular matrix organization; negative regulation of Notch signaling pathway; positive regulation of B cell differentiation; positive regulation of myotube differentiation; protein processing; skeletal system development; anatomical structure morphogenesis; angiogenesis; astrocyte cell migration; cellular response to genistein; endothelial cell proliferation; male gonad development; negative regulation of focal adhesion assembly; ossification; and 10 more
Cellular component: cytoplasm; cytoplasmic vesicle; extracellular region; focal adhesion; macropinosome; melanosome; nucleus; plasma membrane; Golgi lumen; extracellular matrix
Genetic constraint (gnomAD): Loss-of-function variants: 13 observed, 66.21 expected, observed/expected ratio (o/e) 0.2, 90% interval 0.13 to 0.31. The upper end of that interval is the gene's LOEUF score, 0.31, which puts it in group 1 of 6, group 1 being the genes least tolerant of losing a copy. Missense variants: 586 observed, 796.43 expected, observed/expected ratio (o/e) 0.74, 90% interval 0.69 to 0.79. Synonymous variants: 319 observed, 320.63 expected, observed/expected ratio (o/e) 0.99, 90% interval 0.91 to 1.09.
Homologues: Orthologues: chimpanzee MMP14 (99% identical), macaque MMP14 (99% identical), pig MMP14 (97% identical), dog MMP14 (97% identical), rat Mmp14 (97% identical), mouse Mmp14 (97% identical), guinea pig MMP14 (95% identical), tropical clawed frog mmp14 (75% identical), zebrafish mmp14b (68% identical), zebrafish mmp14a (66% identical), Caenorhabditis elegans zmp-3 (26% identical), Caenorhabditis elegans zmp-4 (20% identical), and 3 more. Paralogues in human: MMP15 (57% identical), MMP16 (55% identical), MMP24 (54% identical), MMP25 (35% identical), MMP17 (33% identical), MMP3 (32% identical), MMP12 (32% identical), MMP1 (31% identical), MMP10 (31% identical), MMP13 (31% identical), MMP2 (31% identical), MMP20 (30% identical), and 11 more.
Diseases named in the same sentence as MMP14 in open-access papers:
MMP14 is named in the same sentence as 360 diseases in open-access papers, as found by Europe PMC text mining. Sharing a sentence is not in itself a finding about the gene and the disease. The quoted sentences say what the papers report.
breast carcinoma (233 papers, 2004 to 2026). "For example, a cell-associated EPHA2 ∼60 kDa fragment generated by MMP14-mediated cleavage in the FN1 domain has been implicated in breast cancer cell invasiveness through S897 phosphorylation." (PMID 39706267, 2024). "Within the TME, cancer-associated fibroblasts (CAFs) also express MMP-14 and thereby contribute to invasion and metastasis, as shown in a murine breast cancer model." (PMID 35008569, 2021). "An MMP14-deficient breast cancer mouse model showed reduced metastasis; an effect attributed to the reduced collagen I degradation by stromal fibroblasts." (PMID 31466240, 2019). "MMP‐14 is of particular interest because this enzyme is involved in multiple events linked to breast cancer invasion, such as basement membrane breaching, tumor invasion, intracellular trafficking and cell motility regulation." (PMID 30186741, 2018). "To assess the specific effects of our selective inhibitors on each MMP, we utilized the MCF-7 breast cancer cell line that is naturally MMP14- and MMP9-deficient." (PMID 30174795, 2018). "For instance, in vitro studies showed that MCF7 breast cancer cells cotransfected with MMP14/β3-integrin caused platelet aggregation via introduced MT1-MMP/MMP14 and via activation of MMP2." (PMID 28785589, 2017). "For example, the expression of MMP9, MMP13 and MMP14 all correlated with poor survival in patients with breast cancer, and expression of MMP1 and MMP2 was associated with highly aggressive breast cancer that metastasizes rapidly to the lung." (PMID 26956475, 2016). "Additionally, cell surface PGs (SDC1 and SDC4) and MMPs (MMP2, MMP7, MMP9, and MMP14) implicated in breast cancer progression were further included." (PMID 41228316, 2025). "Furthermore, elevated levels of MMP14 were associated with poor prognosis and invasiveness in breast cancer." (PMID 32575583, 2020). "In addition, in a study of 18 breast cancer patients and 11 healthy controls, the serum MMP-14 levels determined using an enzyme-linked immunosorbent assay were significantly higher in cancer patients than in controls." (PMID 30532247, 2018). "Of the MMP-14/TIMP-2/MMP-2 complex, MMP-14 was the factor most significantly associated with the outcome of breast cancer and was an independent factor of poor overall survival when adjusted for clinical prognostic factors, but not for certain ancillary markers." (PMID 16776850, 2006). "YBX1 induces increased expression of MMP14 in breast cancer, and overexpression of YBX1 leads to more locally invasive, lung metastatic and highly lethal breast cancer cells." (PMID 41507135, 2026). "The tissue-specific nature of MMP-14 function is further evident when comparing ACC to breast cancer." (PMID 41542511, 2026). "Prior studies in breast cancer cells demonstrated that MMP-14 modulates DNA damage response through stimulation of integrinβ1, which activates ERK and AKT signaling cascades." (PMID 41542511, 2026). "In the verification cohort, IgG autoantibodies against HSPA4, ENO1, PRDX6, PRPF19 and MMP14 were significantly increased in breast cancer patients with areas under the curve (AUCs) of 0.90, 0.89, 0.82, 0.78 and 0.77, respectively." (PMID 40766308, 2025). "The lactate transporter protein MCT4, in conjunction with CD147, is implicated in the matrix metalloproteinase 14 (MMP14)-mediated degradation of the extracellular matrix (ECM), thereby facilitating breast cancer cell invasion." (PMID 40165895, 2025). "Five potential AAb biomarkers (HSPA4, ENO1, PRDX6, PRPF19, MMP14) predictive of breast cancer were identified through verification and validation cohorts." (PMID 40766308, 2025). "The Mann-Whitney U test showed that five AAbs (HSPA4, PRPF19, ENO1, PRDX6, and MMP14) were significantly higher in the breast cancer group than in the control group." (PMID 40766308, 2025). "We validated these five autoantibodies (HSPA4, ENO1, PRDX6, PRPF19, and MMP14) in an independent cohort of 33 breast cancer patients and 45 healthy controls." (PMID 40766308, 2025).
breast carcinoma (continued). "Anti-HSPA4, anti-PRPF19, anti-ENO1, anti-PRDX6, and anti-MMP14 autoantibodies showed significant increases in breast cancer patients." (PMID 40766308, 2025). "For the matrix degradome, MMP1, MMP2, MMP10 and MMP14 showed trends of progressive upregulation with increasing metastatic potential in lung fibroblasts exposed to secreted factors from breast cancer cells." (PMID 37903851, 2023). "MMP-14 is reported to be important in the migration of multiple types of cancer, with mutations in MMP-14 leading to a decrease in PCa migration in vitro and peptide inhibitors of MMP-14 decreasing breast cancer invasion in vitro and metastasis in vivo." (PMID 37025604, 2023). "In particular, MMP-14 has a critical regulatory role and is overexpressed in neuroblastoma, carcinoma, ovarian cancer, and breast cancer." (PMID 37047831, 2023). "Expression levels of ECM degrading proteases MMP2, MMP3, and MMP14 significantly increased in lung fibroblasts exposed to media conditioned by metastatic breast cancer cells as compared to controls." (PMID 37903851, 2023). "MiR-181a are known to inhibit migration and angiogenesis through the regulation of MMP-14 in SK-3 breast cancer cells." (PMID 38201092, 2023). "In vivo studies confirmed that the four d-glutamate-glycine-glycine repeat sequence has specific proteolytic activity in breast cancer (MDA-MB-231) cells transfected with MMP-14 cDNA to overexpress MMP-14." (PMID 37047831, 2023). "It has been shown that MMP2 and MMP14 are expressed selectively in leader cells during collective invasion, and the knockdown of MMP14 inhibited fibrosarcoma and breast cancer cell collective invasion." (PMID 37490147, 2023). "Alternative studies using breast cancer cells have shown that CIP4 suppresses Src-induced invadopodia formation by promoting endocytosis of MT1-MMP (also known as MMP14)." (PMID 37132654, 2023). "In an intraductal xenograft model, MMP-14 was found to be required for cancer progression from carcinoma in situ to the invasive stage in basal-like breast cancer." (PMID 36741729, 2022). "We proved previously that the activation of NK1R stimulated the expression and activities of MMPs like MMP2 and MMP14, involving the migration of glioblastoma, melanoma, and breast cancer cells." (PMID 35013118, 2022). "Upregulation of MMP-14, a membrane-anchored MMP, is associated with an increased risk of metastasis in breast cancer." (PMID 36741729, 2022). "Of note, membrane type 1-MMP (MT1-MMP; also designated MMP-14) has important roles in matrix turnover and regulates key functional characteristics of breast cancer cells, such as migration, invasion and angiogenesis." (PMID 35260891, 2022). "Targeting MMP14 with antibody demonstrates great efficacy in limiting breast cancer growth and metastasis." (PMID 35223528, 2022). "DX-2400 was further validated to reduce primary tumor growth in orthotopic murine breast cancer models and was found to improve the response to radiotherapy in MMP-14-high-expressing 4T1 tumors." (PMID 36741729, 2022). "In turn, the proteolytic activity of MMP14 releases the ENG at the breast cancer cell membrane, promoting their migratory potential by upregulating the SMAD2/3 pathway." (PMID 33804796, 2021). "The transmembrane MT1-MMP (MMP14) has important roles in matrix turnover and regulates key functional properties of breast cancer cells, such as migration, invasion and angiogenesis." (PMID 33809973, 2021). "Western blotting was used to detect the expression of E-cadherin, N-cadherin, vimentin, MMP2 and MMP14 in different functional models of breast cancer subtypes to verify the occurrence of EMT." (PMID 33591943, 2021). "It has been shown that MMP14 takes part in epithelial-mesenchymal transition and promoted the progression of various cancers, such as hepatocellular carcinoma, breast cancer, glioma, and sarcoma." (PMID 33564303, 2021).
breast carcinoma (continued). "For instance, MMP14 empowered tumor-initiating breast cancer cells under hypoxic nutrient-depleted conditions." (PMID 34868395, 2021). "Consistent with the observations of the tumor cell lines and xenograft models, the distribution and intensity of GABARAP negatively correlated with MMP2 (P=0.0013) and MMP14 (P=0.019) in breast cancer tissue specimens." (PMID 33591943, 2021). "TKS5, integrin, F-actin, cortactin, and MMP-14 were identified as prognostic markers related to invadopodia and their targeting curbs breast cancer metastasis." (PMID 35008569, 2021). "In this process, TGFβ1 secreted by malignant breast cancer cells acts through a paracrine mechanism on BM-MSCs to induce the production of soluble MMP14." (PMID 33804796, 2021). "Presently, the MMP-14 blocking antibody DX-2400 has been tested in a murine model of breast cancer, where it inhibited primary tumor growth when administered alone and further impaired the growth when combined with radiotherapy." (PMID 34956886, 2021). "MMP-14 has been shown to be regulated in breast cancer, where it is reported to activate MMP2 that is, in turn, associated with increased risk of malignancy and metastasis." (PMID 34314429, 2021). "Lumican has an anti-tumor effect in breast cancer, pancreatic cancer, and malignant melanoma by counteracting MMP-14 signaling, among other things." (PMID 35008569, 2021). "In MDA-MB 231 breast cancer cells, the transport of vesicles with MMP-14 to the cell surface is triggered by the binding of β1 integrins to collagen in a Rab8-GTPase-dependent manner." (PMID 35008569, 2021). "Low MMP14 expression can inhibit the invasion and metastasis of breast cancer and gastric cancer cells." (PMID 34587931, 2021). "The CD44 signalling pathway can upregulate MMP-14 expression in basal-like breast cancers, whereby this upregulation correlates with the induction of basal-like breast cancer cells invasiveness." (PMID 34944493, 2021). "Some of them, such as MMP-2, MMP-9 and MMP-14 are overexpressed in breast cancer, inducing collagen degradation and promoting metastasis." (PMID 32984031, 2020). "ADAM12 and MMP‐14 have been found to be related to cavernous sinus invasion in human PA tissue samples as well as to growth in other tumors, for example, breast cancer." (PMID 33030286, 2020). "CAIX interacts with α2/β1, α3/β1, and α6/β1 integrins as well as MMP14, and it is located in breast cancer cell mature invadopodia to induce matrix acidification and promote degradation." (PMID 31052560, 2019). "Hypermethylated MMP14 and MMP2 promoters have been found in the non-invasive MCF7 breast cancer cell lines, whereas highly migratory glioma cells display hypomethylated promoters coupled to high MMP14 and MMP2 expression levels." (PMID 31466240, 2019). "We analyzed 1000 human breast cancer specimens and 59 human breast cancer cell lines and found that levels of Ets1 expression is well-correlated with Eng and Mmp14 levels, accordingly." (PMID 30467308, 2018). "Further analysis using a proximity ligation assay (PLA) has confirmed these results, demonstrating that CAIX and MMP14 reside in close proximity to one another in breast cancer cells." (PMID 29517989, 2018). "In accordance with this observation, silencing ZO-1 has been previously reported to downregulate MMP14 expression in human breast cancer cells." (PMID 29765546, 2018). "Altogether these observations suggest that EDP treatment increases the presence of MMP‐14 at the cell surface of the breast cancer cells." (PMID 30186741, 2018). "Text mining of PubMed literature with an R package RISmed revealed that most of them are with unclear roles in breast cancer except for Igfbp3, Mmp14, Fap, Timp3 and Wnt5a." (PMID 29615825, 2018). "In particular, we identified JUN, FADD, NFKB1, Bcl-2, GNAO1, and MMP14 as potential targets of EGCG in breast cancer." (PMID 28713815, 2017).